VLDLR (very low density lipoprotein receptor)
Diseases named in the same sentence as VLDLR in open-access papers (continued):
Sharing a sentence is not in itself a finding about the gene and the disease.
atherosclerosis (10 papers, 2015 to 2025). A disease characterized by the build-up of fatty material and calcium deposition in the arterial wall resulting in partial or complete occlusion of the arterial lumen. "Specifically, it has been reported that transplantation of VLDLR-expressing macrophages into VLDLR-deficient mice accelerated atherosclerosis development." (PMID 26317415, 2015). "Studies indicated that the reconstitution of VLDLR expression in macrophages of VLDLR-deficient mice promotes the occurrence and development of atherosclerosis, which may be due to the accumulation of atherosclerotic lipoproteins caused by the knockout of VLDLR." (PMID 33868316, 2021). "As the full length reelin (~400-kd) or its central fragment R3-6 (340 kd) is too large to be used in gene transfer studies, the reelin subregion R5-6 (~88kd) could be a valuable tool in future studies for investigating the effect of VLDLR/apoER2 on atherosclerosis in animal models." (PMID 26317415, 2015). "While the decreased levels of very low-density lipoprotein receptor (VLDLR), apolipoprotein B (ApoB), apovitellenin 1 (ApoVLDlII), and vitellogenin (VTGI, VTGII, and VTGIII) genes expressed in the ovary are indicative of atherosclerosis, they do not explain the disease." (PMID 41585947, 2025).
Dysequilibrium syndrome (9 papers, 2012 to 2025). "Previously we have reported that missense mutations in the Very Low Density Lipoprotein Receptor gene (VLDLR), causing Dysequilibrium syndrome (DES), disrupt ligand-binding, due to endoplasmic reticulum (ER) retention of the mutants." (PMID 29371607, 2018). "Our data expand the mutation spectrum of dysequilibrium syndrome, VLDLR type, and demonstrate the presence of a missense founder mutation in patients with this syndrome in the southeastern part of the Arabian Peninsula." (PMID 22973972, 2012). "In this article, we report the identification of a novel founder missense mutation in VLDLR gene in two consanguineous unrelated Omani families with Dysequilibrium syndrome, VLDLR type (CAMRQ1, OMIM 224050)." (PMID 22973972, 2012). "We have delineated the phenotype associated with dysequilibrium syndrome in two Omani families and identified the first homozygous missense pathogenic mutation in VLDLR gene with likely founder effect in the southeastern part of the Arabian Peninsula." (PMID 22973972, 2012). "CAMRQ syndrome can arise from pathogenic variants in several genes including the very low‐density lipoprotein receptor (VLDLR) (CAMRQ1; MIM: 224050), WD repeat domain 81 (WDR81) (CAMRQ2; MIM: 610185), carbonic anhydrase 8 (CA8) (CAMRQ3; MIM: 613227) and ATP8A2 designated as CAMRQ4 (MIM: 615268)." (PMID 39931767, 2025). "Thus the clinical phenotype of the dogs reflects VLDLR-associated cerebellar hypoplasia in humans, who display severe truncal ataxia (dysequilibrium syndrome) as the main clinical manifestation." (PMID 25668516, 2015). "The p.Asp487Tyr mutation in VLDLR could explain the neurological phenotype, classifying the affected individuals as VLDLR-associated Dysequilibrium Syndrome (DES), a rare condition with eight disease-causing (two missense) mutations reported to-date." (PMID 24498604, 2013). "We identified a novel mutation, p.Asp487Tyr, in the VLDLR gene involved in the Reelin developmental pathway and associated with a rare form of LCH, the Dysequilibrium Syndrome." (PMID 24498604, 2013). "Research has found that homozygous loss-of-function mutations in VLDLR lead to dysequilibrium syndrome, a non-progressive cerebellar ataxia syndrome associated with intellectual disability." (PMID 38831425, 2024).
breast carcinoma (8 papers, 2010 to 2024). "Reduced miRNA-1297 was associated with decreased VLDLR expression in highly progressive breast cancer." (PMID 35457118, 2022). "Moreover, high expression of VLDLR was associated with poor prognosis of patients with breast cancer." (PMID 36568166, 2022). "VLDLR was also included in our model as a protein encoded by an upregulated metabolism gene Vldlr upon CR with dual functions in lipid metabolism and as a pro-oncogene in gastric cancer, breast cancer, liver adenocarcinoma, and other cancers." (PMID 34202278, 2021). "In the current study, we observed high expression of VLDLR in part of the breast cancer tissues, particularly in triple-negative breast cancer tissues, and reduced expression of VLDLR in normal breast tissues." (PMID 36568166, 2022). "To explore the role of VLDLR in breast cancer, we examined the expression levels of VLDLR in 146 cases of breast cancer tissues and 30 control subjects by immunohistochemistry." (PMID 36568166, 2022). "Consistently, our data revealed that silencing endogenous VLDLR inhibited cell proliferation and colony formation ability in breast cancer cells, whereas VLDLR-I and VLDLR-II overexpression caused the opposite effects." (PMID 36568166, 2022). "VLDLR silencing induced transition to quiescence of breast cancer cells in a ligand-independent manner, blunting cell proliferation in vitro and in vivo." (PMID 36568166, 2022). "In breast cancer cells, VLDLR silencing suppresses sphere formation abilities in vitro and tumor growth in vivo." (PMID 36568166, 2022). "Collectively, our findings provided convincing evidences that VLDLR can serve as a promising target for breast cancer therapy." (PMID 36568166, 2022). "All these provide strong evidence for proposing VLDLR as a potential target for breast cancer treatment." (PMID 36568166, 2022). "VLDLR was upregulated in breast cancer tissues, especially TNBC tissues, and high expression of VLDLR predicts poor breast cancer prognosis." (PMID 36568166, 2022). "Other studies have investigated the role of miRNAs in breast cancer and their relationship to VLDLR expression." (PMID 35457118, 2022). "We further analyzed overall survival of breast cancer patients in separated subtypes and found that high VLDLR expression significantly correlated with poor prognosis in TNBC patients in contrast to other subtypes." (PMID 36568166, 2022). "Here, we unveil two splice variants of very-low-density lipoprotein receptor, VLDLR-I and -II, which are highly expressed in breast cancer stem cells." (PMID 36568166, 2022). "VLDLR silencing induced transition to quiescence of breast cancer cells in a ligand- and lipid-independent manner." (PMID 36568166, 2022). "Overexpression of VLDLR has been reported in numerous types of cancer, including breast cancer, in which VLDLR-II was predominantly expressed." (PMID 36568166, 2022). "We demonstrated that targeting the expression of VLDLR in breast cancer cells dramatically decreased the sphere formation capacity in vitro and tumor growth in vivo, suggesting that VLDLR plays a critical role in the BCSC phenotype." (PMID 36568166, 2022). "To investigate the biological effect of different subtypes of VLDLR on breast cancer cell stemness, we stably overexpressed VLDLR-I/II in MDA-MB-231 cells and found that the sphere formation capabilities were significantly enhanced by both VLDLR-I and VLDLR-II expression." (PMID 36568166, 2022). "Collectively, these findings indicate that VLDLR may be an important therapeutic target for breast cancer treatment." (PMID 36568166, 2022). "Taken together, VLDLR is essential for breast cancer cell proliferation." (PMID 36568166, 2022). "Moreover, high expression of VLDLR in breast cancer tissues correlates with poor prognosis of patients." (PMID 36568166, 2022). "We then investigated whether these functions are involved in VLDLR-mediated promotion of breast cancer cell growth." (PMID 36568166, 2022).
breast carcinoma (continued). "VLDL, a ligand of VLDLR, promotes breast cancer cell proliferation, metastasis, and angiogenesis." (PMID 36568166, 2022). "Furthermore, in this stable cell line, the percentage of cells with high mVenus fluorescent intensity was significantly increased following VLDLR knockdown, indicating that VLDLR silencing promoted breast cancer cells to enter a quiescent state." (PMID 36568166, 2022). "Results indicated that VLDLR inhibition induced quiescence in breast cancer cells." (PMID 36568166, 2022). "Furthermore, VLDLR mRNA was significantly upregulated in moderately and poorly differentiated breast cancer tissues compared to well-differentiated compartments." (PMID 36568166, 2022). "No significant change in proliferation of MDA-MB-231 cells was found after GST-RAP treatment, indicating that ligand-independent activities may be involved in VLDLR-mediated promotion of breast cancer cell growth." (PMID 36568166, 2022). "Therefore, we concluded that the entry of cellular quiescence contributed to VLDLR knockdown-mediated breast cancer cell growth inhibition." (PMID 36568166, 2022). "Previous studies have confirmed that high VLDLR expression is correlated with lymph node and distant metastasis in gastric and breast cancer patients, that VLDLR may be a clinical marker in cancers, and has a potential link with β-catenin signaling pathway." (PMID 34256750, 2021). "Furthermore, high expression of VLDLR was associated with poor overall survival and relapse-free survival in breast cancer patients, suggesting that VLDLR could be considered as a potential therapeutic target for breast cancer therapy." (PMID 36568166, 2022). "Furthermore, in breast cancer tissues, the expression of VLDLR mRNA exhibits positive correlations with gene signatures constituted by genes involved in these pathways, suggesting that VLDLR expression correlated with elevated energy production and ribosome biogenesis." (PMID 36568166, 2022). "We then investigated whether VLDLR knockdown induced cell apoptosis in breast cancer cells." (PMID 36568166, 2022). "Although low/negative expression of VLDLR (H-score ≤ 20) was observed in more than half of the breast cancer cases, positive expression of VLDLR (H-score > 20) occurred more frequently in breast cancer tissues than in tumor adjacent normal breast tissues." (PMID 36568166, 2022). "Conversely, we found a downregulation of VLDLR, whose genetic or epigenetic silencing contributes to gastric carcinogenesis, CYP27A1, which induces T cell dysfunction, thus promoting breast cancer progression and CCL2, downregulated in diffuse gastric cancer primarily in advanced stages." (PMID 34012923, 2021). "As expected, VLDLR knockdown did not inhibit lipid accumulation in breast cancer cells." (PMID 36568166, 2022).
steatosis (8 papers, 2007 to 2025). Increased lipid within the cytoplasm of cells. "Activation of the PERK pathway increased very low density lipoprotein-receptor (VLDLR) expression which increased lipoprotein delivery to the liver and steatosis." (PMID 41196673, 2025). "Activation of the PERK-ATF4 pathway under ER stress condition is required for hepatic VLDLR upregulation in hepatocytes, which is responsible for hepatic steatosis." (PMID 30254132, 2018). "In LCKD-fed wild-type mice, induction of hepatic VLDLR expression and decreased serum LPL activity inhibit the transport of triglycerides by VLDL from the liver to extrahepatic tissues, ultimately promoting steatosis." (PMID 31815184, 2019).
Lissencephaly (7 papers, 2007 to 2023). A spectrum of malformations of cortical development caused by insufficient neuronal migration that subsumes the terms agyria, pachygyria and subcortical band heterotopia. "Among them, frontal predominant mild lissencephaly (diffuse pachygyria) with severe hippocampal and cerebellar hypoplasia or Reelin-type lissencephaly is caused by mutation of either RELN or VLDLR and shows autosomal recessive inheritance." (PMID 26052266, 2015). "It has recently been reported that VLDLR deletions in humans result in a neurological disorder characterized by lissencephaly and cerebellar hypoplasia, malformations similar but less severe than those associated with RELN deletions." (PMID 17330141, 2007). "Mutations of many genes are involved in neuronal migration disorders, such as LIS1 and DCX in classical lissencephaly spectrum, TUBA1A in microlissencephaly with agenesis of the corpus callosum, and RELN and VLDLR in lissencephaly with cerebellar hypoplasia." (PMID 26052266, 2015).
diabetes (6 papers, 2011 to 2025). "Further, the present study identified that ectodomain shedding of VLDLR is suppressed by hypoxia and in diabetes, which may contribute to the overactivation of Wnt signaling in diabetic complications." (PMID 27528615, 2016). "Most importantly, we found that VLDLR ectodomain shedding is reduced under hypoxia and in diabetes, which may contribute to the aberrant regulation of Wnt signaling in diabetic complications." (PMID 27528615, 2016). "Interestingly, the levels of circulating sVLDLR-N were decreased in both 3-month-old Akita mice and 6-month-old db/db mice, suggesting reduced VLDLR ectodomain shedding under diabetes conditions." (PMID 27528615, 2016). "It accelerates diabetes mellitus-mediated myocardial stress and dysfunction by enhancing insulin resistance, CD36, and VLDLR (very low-density lipoprotein receptor) expression." (PMID 36613495, 2022).
Hypercholesterolemia (6 papers, 2010 to 2024). An increased concentration of cholesterol in the blood.
Insulin resistance (6 papers, 2011 to 2022). Increased resistance towards insulin, that is, diminished effectiveness of insulin in reducing blood glucose levels. "In conclusion, we have demonstrated that macrophage VLDLR plays important roles in mediating chronic inflammation and insulin resistance in DIO." (PMID 29057873, 2017). "Adoptive transfer of VLDLR knockout bone marrow to wild-type mice relieves adipose tissue inflammation and improves insulin resistance in diet-induced obese mice." (PMID 29057873, 2017). "Notably, we discovered that deletion of VLDLR in hematopoietic cells would be sufficient to alleviate systemic insulin resistance in DIO." (PMID 29057873, 2017). "Moreover, bone marrow transplantation (BMT) from VLDLR knockout (KO) mice into wild-type (WT) recipient mice attenuates insulin resistance in diet-induced obesity (DIO), simultaneously with reduced adipose tissue inflammation." (PMID 29057873, 2017).
Alzheimer disease (5 papers, 2011 to 2022). A progressive, neurodegenerative disease characterized by loss of function and death of nerve cells in several areas of the brain leading to loss of cognitive function such as memory and language. "ApoER2 and VLDLR were recently identified as receptors for Clusterin (apolipoprotein J) which has been implicated in Alzheimer disease and cancer." (PMID 30304853, 2018). "It is notable that the receptors for this pathway are two lipoprotein receptors, VLDLR (Very Low Density Lipoprotein Receptor) and ApoER2 (Apolipoprotein E2 Receptor), the latter of which has been implicated in Alzheimer’s disease." (PMID 27658289, 2016). "For example, ε4 allele carriers have an increased prevalence of Alzheimer’s disease, and a deficiency in signaling transduction involving VLDLR/apoER2-Dab1 has been suggested as a mechanism involved in Alzheimer’s disease." (PMID 22984509, 2012). "In addition to its important regulatory role in lipid metabolism, VLDLR is found associated with insulin resistance and is involved in multiple diseases such as diabetic retinopathy, atrial fibrillation, hypertensive cardiomyopathy, and Alzheimer’s disease." (PMID 35457118, 2022). "Recent studies have revealed the ability of VLDLR to interact with multiple ligands and molecules such as reelin and clusterin, which are correlated with Alzheimer’s disease." (PMID 35457118, 2022). "Since Reelin and apolipoprotein E, are ligands of ApoER2 and VLDLR, these receptors are of interest with respect to Alzheimer’s disease." (PMID 30304853, 2018). "The involvement of VLDLR in Alzheimer’s disease has been observed in clinical observations." (PMID 35457118, 2022). "Currently, it is suggested that VLDLR is able to interact in the onset and progression of Alzheimer’s disease without the interaction of VLDL." (PMID 35457118, 2022).
Cerebellar hypoplasia (5 papers, 2015 to 2024). Cerebellar hypoplasia is a descriptive term implying a cerebellum with a reduced volume, but a normal shape and is stable over time. "Pathogenic VLDLR variants in patients with the typical cerebellar hypoplasia phenotype affect exons that are present in all four transcript variants." (PMID 39085459, 2024). "In two unrelated Emirati families of Omani origin with VLDLR-Associated cerebellar hypoplasia (OMIM# 224050), identified the same missense variant, NM_003383.5:c.2117G>T, on a shared haplotype block." (PMID 37214420, 2023). "Our results enable genetic testing and the eradication of this inherited disease in the Eurasier dog population and provide a defined animal model to develop a better understanding for VLDLR associated cerebellar hypoplasia and dementia in humans." (PMID 25668033, 2015). "VLDLR-associated cerebellar hypoplasia is an autosomal recessive genetic form of non-progressive congenital ataxia." (PMID 31805691, 2019).
hepatocellular carcinoma (5 papers, 2017 to 2024). A malignant tumor that arises from hepatocytes. "The pharmacological inhibition or gene knockdown of SIRT1 upregulated VLDLR protein levels in the human Huh-7 hepatoma cell line, with this increase abolished by the pharmacological inhibition of HIF-1α." (PMID 38807218, 2024).
Sepsis (4 papers, 2011 to 2025). Sepsis is defined as life-threatening organ dysfunction caused by a dysregulated host response to infection. "In the present research, several genes linked to ER stress-response genes were identified, including PRDM16, WRAP53, LTF, and VLDLR, which exhibited increased expression in sepsis." (PMID 40867920, 2025). "In septic foals, several genes, including PRDM16, WRAP53, LTF, and VLDLR, were activated to address inflammation or enhance survival rates in sepsis." (PMID 40867920, 2025). "The present study also identified a notable increase in VLDLR expression during sepsis." (PMID 40867920, 2025). "Lipopolysaccharide may be sequestered in adipose tissue through the very-low-density lipoprotein receptor, and this sequestration could play a role in enhancing survival rates during sepsis." (PMID 40867920, 2025).